IL22 (interleukin 22)
Diseases named in the same sentence as IL22 in open-access papers (continued):
Sharing a sentence is not in itself a finding about the gene and the disease.
infection (continued). "This is a possible mechanism for a reduction in IL-22 mRNA and protein levels observed in ventilated rats that had elevated levels prior to infection with P. aeruginosa." (PMID 32637365, 2020). "Further analysis revealed that lungs from Il22−/− mice infected with H. capsulatum only presented significantly lower concentrations of LTB4 on the 2nd day after infection." (PMID 32517114, 2020). "Luciferase re- porter vectors containing different regions of IL22 mRNA were co- transfected with pcDNA3.1-LINC00662 infection in HCT29, LS174T, LOVO, and CT26 cells." (PMID 31900207, 2020). "The infection of neonates resulted in an elevation of IL-22 expression in the spleen and brain at 2 and 13 dpi, respectively." (PMID 32843067, 2020). "- The IL-22-positive cells are increased in number in the hindgut and head kidney after infection by F. columnare." (PMID 33178219, 2020). "The IL-23/IL-17 axis is essential in the resolution of infection by Candida albicans, Staphylococcus aureus, and Bordetella pertussis, and IL-23-induced IL-22 production is involved in the clearance of lymphocytic choriomeningitis virus (LCMV) infection." (PMID 32906785, 2020). "CD4+ T cells, acting through IL-22, play a crucial role as a defense mechanism against Cr infection." (PMID 32230738, 2020). "Owing to pivotal role of IL-22 in normal biological functions, any impairment in its activity can lead to chronic inflammatory diseases, disturbed wound healing, infections, and cancers." (PMID 33042126, 2020). "In contrast, IL-1β, IFN-γ, IL-22, IL-10, IL-27 and IL-35 were present in lower levels in the lungs of these mice at all post-infection periods assessed." (PMID 32647342, 2020). "Thus, we hypothesized that IL-22 deficiency could impair LTB4 production during infection." (PMID 32517114, 2020). "This inhibitory effect contrasts previous findings in rainbow trout gills after infection with A. salmonicidae, where IL-22 was strongly upregulated." (PMID 33013908, 2020). "Like other cytokines, IL-22 plays pivotal role in generating innate immune response against various infections." (PMID 33042126, 2020). "Focused use of floxed IL-22Ra1 mice should enable high resolution study of tissue and cellular compartments where IL-22 signaling is required during infection." (PMID 32582219, 2020). "Here, IL-23 is needed to induce IL-22 during the infection, and Reg family proteins induced by IL-22 are pivotal in the survival of the host against the infection." (PMID 33003458, 2020). "We observed a significant reduction in the gene expression of α-defensin-1 (Defa1) in the lungs of Il22−/− mice after 14 days of infection." (PMID 32517114, 2020). "By using single cell RNA sequencing, the authors identified distinct clusters of IFN-γ-producing NK cells and Il17a+Il22+ICOS+ ILC3 to be critical for the host resistance in this infection." (PMID 32887435, 2020). "We observed down regulation of IL-22 and IL-10 in spleen of salmon at chalimus stage of infection and an increase in IL-1β, TNF-α and IL-8 at subsequent pre-adult stage in group 2." (PMID 33006991, 2020). "Consistent with the results of this study, after 7 days of infection, the anti-IL-17A, anti-IL-22, and anti-IL-17A + anti-IL-22 groups showed more severe organ damage than the model group." (PMID 33178181, 2020). "These discoveries were replicated in the IL22 data, with the exception that CM+/+ (infections performed in PBMC and co-cultures) contained an insignificantly greater quantity of IL22." (PMID 33116165, 2020). "During infections, neutrophil serine proteases also can degrade IL-22Ra1 providing another mechanism of control of IL-22 signaling." (PMID 32582219, 2020). "In group 3, down regulation of IL-22 and IL-10 was seen in spleen at pre-adult stage of infection (28 dpi), which in turn is related to the increase observed in pro-inflammatory cytokines at adult stage (50 dpi)." (PMID 33006991, 2020).
infection (continued). "It is well known that IL-22 producing CD4+ T cells are essential for controlling Cr infection; however, the T cell-derived cytokines (IL17A, IFN-γ and TNF-α) contribute to intestinal tissue injury either directly or indirectly." (PMID 33076301, 2020). "Mice infected with Cr had increased expression of multiple cytokines including IL-17A, IL-22, IL-6, and IL-1β mRNA in colonic tissue 12 days after infection." (PMID 32230738, 2020). "In a recent study, induction of the expression of the IL-22 protein was also observed in the gills of trout post-infection with A. salmonicida." (PMID 33178219, 2020). "In SGPV-infected gills we see a coordinated suppression of CCL20 and IL-22 in the early phase of infection (E-III), and the γδ T-cell marker TCR Fcγ, is also suppressed during the peak of infection." (PMID 33013908, 2020). "I3C acts by protecting the host against Cr-infection by maintaining IL-22 levels and reducing expression of other pro-inflammatory cytokines, likely through an AhR-dependent pathway." (PMID 33076301, 2020). "In that study, the infection was shown to increase the number of IL-22 producing cells in the gill epithelium and interbranchial lymphoid tissue." (PMID 33013908, 2020). "Using mycelial propagules (conidia and hyphal fragments), the production of IL-22 was increased at 12 h, 7 and 28 days post-infection in Balb/c mice." (PMID 32517114, 2020). "We further carried out qRT-PCR assays to examine the transcriptional regulation of known virulence genes disrupting TJ dynamics during CR infection in Il22-/- mice." (PMID 31251784, 2019). "Consistent with previous findings, wild-type CR infection in Il22-/- mice led to 100% mortality within 14 days post inoculation (dpi)." (PMID 31251784, 2019). "Interleukin-22 (IL-22) is a critical cytokine for host immunity and barrier homeostasis during infection and inflammatory diseases." (PMID 31108847, 2019). "IL-22 contributes to tissue healing processes and promotes innate immune responses to limit damage during infections." (PMID 31809521, 2019). "Infection of 4-week-old ApcMin/+ mice with Citrobacter rodentium, a colonic attaching and effacing pathogen that induces a potent IL-22 response, increased colonic tumour burden." (PMID 31770366, 2019). "IL-22 KO mice develop a lethal infection with C. rodentium and IL-22 from ILC3 cells is required for early protection from C. rodentium." (PMID 30723466, 2019). "A number of genes involved in resistance to infection such as il17, il22, and il6 were also increased." (PMID 30867416, 2019). "Following infection with A. salmonicida for 24 h, both IL-22 transcript and protein expression were significantly induced in the gills." (PMID 31306696, 2019). "As expected, wild-type CR infection led to significantly elevated serum levels of FITC-dextran in Il22-/- mice, indicating severe barrier dysfunction." (PMID 31251784, 2019). "As assayed by immunofluorescence staining, CR infection led to a clearly disorganized distribution of claudin-3 on colon tissue sections derived from Il22-/- mice infected with wild-type CR, compared to PBS control, at 7 dpi." (PMID 31251784, 2019). "Unexpectedly, ΔespF CR infection still resulted in substantial infiltration of immune cells and moderate tissue damage in the Il22-/- colons, as illustrated by Hematoxylin and Eosin (H&E) staining-based histological analyses." (PMID 31251784, 2019). "In summary, the main role of IL-22 in the small intestine appears to be protection from infection, through synthesis of antimicrobial proteins, increased mucus production, and oxidative stress." (PMID 31770366, 2019).
infection (continued). "Consumption of ILCs leads to infection by commensal bacteria and systemic inflammation, and these events can be suppressed by modulation of IL-22." (PMID 30804706, 2019). "Increasing evidence suggests that together with IL-17, IL-22 is also a key regulator of homeostasis and epithelial barrier function and combats infections." (PMID 31614857, 2019). "Vitamin D is required for ILC3 derived IL-22 in the colon and the induction of protective Th17 cell expansion following infection." (PMID 30723466, 2019). "During infection, IL-18 levels remained consistently higher in Viperin−/− mice, whereas IL-22 levels increased in WT animals during infection to reach levels comparable with Viperin−/− animals at 6 dpi." (PMID 30665948, 2019). "To assess their effects on the CR burden during infections in vivo, we inoculated them into Il22-/- animals." (PMID 31251784, 2019). "Genes related to resistance to infection, cytotoxicity, cell death, and G protein-coupled receptor signaling such as c3ar1, hif1α, il22, and ifnγ were highly expressed in mice colonized with P. aeruginosa PA14 WT." (PMID 30867416, 2019). "Given the potential of IL-22 to restore the pulmonary barrier and restore lung function after infection, we believe it is important to understand the cells upon which IL-22 will act and mechanisms in which the IL-22Ra1 produced." (PMID 31416461, 2019). "As expected, Il-22 mRNA levels underwent a dramatic increase during infection (>1,000-fold), while IL-22 protein levels also increased." (PMID 31848276, 2019). "IL-22 was instead required for the production of IL-18 late in infection, as the peak production at 14 days post-infection was abrogated in Il22−/− mice." (PMID 31681274, 2019). "As IL-22 promotes NLRC4 activity in infection, this highlights the cross-talk between IL-22 and IL-18 in VVC." (PMID 31681274, 2019). "The mean fluorescence intensity (MFI) of IL-22 was higher in D+ mice (compared to D- mice) at d10 post-infection in both the ILC3 and T cells." (PMID 30723466, 2019). "Downregulation of IL-22BP is most likely necessary to allow IL-22 to function in the case of infections or tissue damage." (PMID 29572462, 2018). "As for TNF-α, the IL-17A and IL-22 increases were likely related to the magnitude of the bacterial burden and stimulus, and they were apparently unable to improve the course of infection." (PMID 30045763, 2018). "Further, serum levels of interleukin (IL)-2, interferon γ, tumor necrosis factor (TNF)-α, IL-12p70, IL-22, IL-17A, and IL-5 increased significantly after infection." (PMID 30564216, 2018). "To investigate lymphocyte activity after infection, we quantitatively determined the presence of IL-2, IFN-γ, TNF-α, IL-4, IL-5, IL-17A, IL-12p70, and IL-22 in mouse sera at day 3, 5, 7, and 9 post-infection; the sera of healthy mice were used as controls." (PMID 30564216, 2018). "This raises the possibility that intact gut microbiota can induce the expression of IL-22 after AIV infection in chickens." (PMID 30181578, 2018). "The major role of IL-22 is to initiate the innate tissue response to bacterial infections and to help tissue repair after infection or inflammation." (PMID 29572462, 2018). "HIV infection depletes mucosal IL-22-producing T-cell subsets during very early stages of infection." (PMID 29996789, 2018). "Protection from early infection is provided by innate lymphoid cells (ILC) that produce IL-22 and IL-17 (ILC3) and clearance of infection requires robust Th17 cell responses." (PMID 30671060, 2018). "Another mechanism to promote tissue repair following infection is the activity of amphiregulin, which acts on the epithelium to induce cell proliferation much like IL-22." (PMID 29988424, 2018). "ILC3, at the early stage of the infection, and Th22 cells, at the later stage of the infection, are the major sources of IL-22." (PMID 30365535, 2018). "To assess if IL-22 cleavage was occurring in vivo, we measured IL-22 levels in murine lungs during infection." (PMID 29720526, 2018).
infection (continued). "Concentrations of TNF-α, IFN-γ, IL-17A, and IL-22 rose sharply in the milk of UI goats when infection was out of control." (PMID 30045763, 2018). "The infection of IL-22 knockout mice results in increased intestinal epithelial damage, systemic bacterial burden and mortality." (PMID 30258450, 2018). "Conversely, in Il9R−/− mice, the IL-22/NLRC4 axis was not only maximally induced but also maintained throughout the infection." (PMID 30515173, 2018). "A 7 fold increase was observed in IL-22 levels at 7 days post-infection and the levels were measured to be about 60 ± 10 pg/ml throughout the infection." (PMID 29896527, 2018). "More importantly, after H9N2 infection, the expression of IL-22 in the probiotic or FMT groups was significantly higher compared to undepleted chickens." (PMID 30181578, 2018). "One of the main hallmarks of infection with C. rodentium is induction of tissue damage repair responses, i.e. elaboration of IL-22, secretion of AMPs and proliferation of transit amplifying cells." (PMID 30365535, 2018). "After infection, significantly up-regulated mRNA expressions of immune-related genes were detected in trout skin as early as 12 h (for IL22) or 24 h (IL2, IgT, IgM, and IgD) and reach their peak levels at 7 d, then recovered to control levels by 28 d." (PMID 30619329, 2018). "Such broad T effector responses that produce IFN-γ, IL-17, IL-22, and perforin appear to be transiently more robust in week 3 and are still appreciable at week 8 when compared with those that occur during infection with the control Erdman strain." (PMID 30538219, 2018). "We addressed the impact of the in vivo administration of recombinant IL-22 before infection on lung damage after infection." (PMID 28887540, 2017). "This supports a protective role of IL-17 and IL-22 during early infection and suggests IL-22 as a potential marker of LTBI." (PMID 29075255, 2017). "Our results show that reduction in IL-22 production by a bacterial toxin is an excellent strategy on the part of the pathogen to establish infection in the host." (PMID 29059238, 2017). "Other publications have suggested that CX3CR1+ MNP, which predominantly differentiate from monocyte precursors, provide essential support in the induction of the IL-22-mediated innate response upon infection with C. rodentium." (PMID 28520792, 2017). "In the context of infection and inflammation, IL‐22 production by ILC3 is induced by cytokine signals derived from bacterial‐sensing myeloid cells, such as IL‐23 and IL‐1β." (PMID 27935637, 2017). "During the early phase of infection, the cytokine IL-22 is essential to confer host protection and RORγt-expressing group 3 innate lymphoid cells (ILC3) have been identified as a critical cellular source of this cytokine." (PMID 28520792, 2017). "We found PFOS prevented the growth of C. rodentium at early stage of infection by promoting IL-22 production from ILC3 in an Ahr-dependent manner." (PMID 28701769, 2017). "Reduced IL-22 in both the inflammatory milieu and systemically would have far reaching effects on the effectiveness of the immune response to combat infection." (PMID 29059238, 2017). "Previous studies highlighted the importance of the cytokine IL-22 for inducing resistance against infection with C. rodentium." (PMID 28520792, 2017). "In IL-22−/− mice, increased intestinal damage, bacterial burden, and mortality was observed on infection with Citrobacter rodentium, and in humans, IL-22 has been shown to protect intestinal epithelium in IBD." (PMID 29326704, 2017). "Infection was associated with particularly marked increases in expression of IFNG (FC: 7.12, p-value: 1.32E-42) and IL22 (FC: 6.49, p-value: 1.6E-23)." (PMID 28966918, 2017). "Our results, illustrated in a graphical summary, suggest that IFNG and IL22 were acutely upregulated in response to C. trachomatis infection and expression appeared to be reduced following the clearance of infection, despite the persistence of inflammation." (PMID 28966918, 2017).
infection (continued). "In animal infection models using these pathogens, IL-22 primarily plays a protective role by maintaining barrier integrity and thereby limiting bacterial dissemination." (PMID 29059238, 2017). "IL-22, which was highly upregulated with infection, is also important in the maintenance of epithelial health and barrier function." (PMID 28966918, 2017). "al. found no role for IL-22 in the murine response to Schistosoma mansoni, whereas goblet cell hyperplasia and mucin secretion, a key effector in the gut, was driven by IL-22 following infection with nematodes." (PMID 27055194, 2016). "IL-17 and IL-22 are both known to be potent inducers of angiogenin-4 from Paneth cells during infection." (PMID 27089535, 2016). "Expression of IL-22 in H. pylori-infected WT mice at 1 month, 2 months and 3 months post infection was measured by real-time rtPCR." (PMID 26867135, 2016). "The analysis of tissue burdens during early infection with 500 parasites revealed an unaltered parasite burden in the spleens and the small intestines and increased burdens in the livers of IL-22−/− mice." (PMID 27650379, 2016). "In the Citrobacter rodentium infection model, which mimics infections by attaching and effacing (A/E) bacterial pathogens in humans, IL-22 is required for the colonic epithelial production of antimicrobial proteins, including RegIIIbeta and RegIIIgamma." (PMID 26977122, 2016). "Whereas both CD4+ and CD8+ T cells produced IFN-γ during T. cruzi infection, only CD4+ T cells were positive for IL-22 at day 14 post infection after unspecific or antigen-specific stimulation." (PMID 27650379, 2016). "While several studies have convincingly shown a preferential loss of intestinal IL-17 and IL-22 producing CD4+ T-cells in HIV and SIV infection, it is unclear how exactly the functions of these cells are perturbed during infection." (PMID 26829644, 2016). "Here, we demonstrate that in vivo infection with M. haemolytica results in increased expression of IL-17, IL-21 and IL-22." (PMID 26942409, 2016). "The increased IFNγ secretion at d3 post PbA infection by CD3+ T cells was confirmed in mice in which IL-22 was transiently neutralized compared to the control group." (PMID 27311945, 2016). "Our study indicated that three cytokines (Fas, PF4 and IL-22) were upregulated in WSSV-infected shrimp at 6 h post-infection." (PMID 27631372, 2016). "M. haemolytica infection results in increased expression of IL-17, IL-22 and IL-23 in the lungs by day 3 after infection." (PMID 26942409, 2016). "Our previous A. butzleri infection studies in gnotobiotic IL-10−/− mice further revealed that in the colon IL-18 mRNA levels were elevated during both the early and late phase of infection, whereas colonic IL-22 mRNA was upregulated during the former only." (PMID 27385977, 2016). "They showed that IL-22 maintains homeostatic IL-18 expression in epithelial cells and IL-8 can be augmented during infection." (PMID 27148267, 2016). "The expression of IL-17 and IL-22 increases at other mucosal sites after infection with a number of pathogens including intestinal infections with Citrobacter rodentium or Salmonella Typhimurium." (PMID 26977122, 2016). "Since T cells are stronger activated in Il22−/− mice during PbA infection it was of interest to analyse if the proliferation of T cells in Il22−/− mice is altered in vivo." (PMID 27311945, 2016). "In recent years, the role that IL-22 plays in antiviral immune responses has been examined in a number of infection models." (PMID 27303405, 2016). "The infection of IL-22 KO mice induced huge congestive inflammatory lesions also mainly composed by mononuclear infiltrates and neutrophils (data not show) that were reduced at a lesser extent with mc2-CMX vaccination." (PMID 27375607, 2016). "The primary roles of IL-17 and/or IL-22 in these models are to control the infection within the mucosa and prevent the dissemination of these pathogens." (PMID 26977122, 2016).